PCSK9 (proprotein convertase subtilisin/kexin type 9)
Diseases named in the same sentence as PCSK9 in open-access papers (continued):
Sharing a sentence is not in itself a finding about the gene and the disease.
tumor (continued). "PCSK9 antibodies have been reported to synergistically inhibit tumor growth with programmed cell death protein 1 (PD-1) inhibitors by promoting intratumoral infiltration of cytotoxic T cells, suggesting that PCSK9 inhibition is a feasible strategy for enhancing immune checkpoint therapy." (PMID 38617549, 2024). "Thus, the inhibition of PCSK9 can suppress tumor development to a certain degree by lowering serum cholesterol levels." (PMID 39324018, 2024). "Inhibition of PCSK9 may also promote intra-tumor T-cell infiltration, thereby making tumors more responsive to immune checkpoint therapy." (PMID 38940622, 2024). "In addition, the immune regulatory role of PCSK9 inhibition was evaluated via in vitro cell coculture and the tumor-bearing mouse model." (PMID 38600469, 2024). "Furthermore, the introduction of small interfering RNA (siRNA) against PCSK9 into human lung adenocarcinoma cells downregulated anti-apoptotic molecules and induced mitochondrial dysfunction, which then hampered tumor activity by promoting cell apoptosis." (PMID 38672532, 2024). "Moreover, PCSK9 inhibition combined with PD-1 antibody therapy enhanced the effect of tumor immunotherapy." (PMID 38398104, 2024). "Since the current PCSK9 inhibitors have been used in clinic, and the incidence of subsequent related tumors in these patients can be compared in a prospective study to help prove the potential of PCSK9 in tumor immunotherapy." (PMID 37860186, 2023). "Therefore, we also suspected that there were three other possible reasons for suppressing tumor growth in the combination of mTOR inhibitors and PCSK9 inhibitors which would be explored in greater detail in our future studies." (PMID 37896137, 2023). "In recent years, PCSK9 has aroused extensive attention in tumor progression." (PMID 37896137, 2023). "In addition, the role of PCSK9 in sepsis, vascular inflammation, and tumor immunity is also receiving increasing attention." (PMID 38093957, 2023). "To conclude, our study demonstrated that high PCSK9 expression in baseline tumor tissue could be a deleterious factor in advanced NSCLC patients receiving ICIs with poorer efficacy." (PMID 37025995, 2023). "Moreover, in our research, tumor growth was further delayed by PCSK9 inhibition in combination with the CD137 agonist with long-term survival of the host mice in the doublet group." (PMID 37025995, 2023). "The PCSK9 protein utilized by tumor can originate from circulation (host) or tumor." (PMID 36588164, 2023). "Our results further detailed that tumor with substantial PCSK9 expression may express different levels at various stages and subtypes, based on the GEPIA and UALCAN databases." (PMID 37860186, 2023). "So, we cannot exclude the possibility that PCSK9 might promote tumor growth by other pathways besides inducing LDL-‍C." (PMID 37898598, 2023). "Our study further analyzed the signal pathways that may performed in the tumorigenesis and revealed the sensitivity of PCSK9 correlated with anti-tumor drugs in tumor treatment and their corresponding targets, such as PAK1, BCL2 and MDM2." (PMID 37860186, 2023). "Evidence thus supports a critical oncogenic function of tumor-derived PCSK9." (PMID 36588164, 2023).
tumor (continued). "Furthermore, PGRN and Pcsk9 levels in CAFs-CM were much higher than that in tumor-CM, therefore we focused the function of PGRN and Pcsk9 in CAFs." (PMID 37898598, 2023). "To confirm the tumorigenic ability of PCSK9, we hypothesized that flubendazole may inhibit tumor growth in a PCSK9 dependent manner." (PMID 37151886, 2023). "Inhibition of PCSK9 by gene deletion or PCSK9 antibody can increase the expression of major histocompatibility protein class I protein on the surface of tumor cells, and promote the strong tumor invasion of cytotoxic T cells." (PMID 37305043, 2023). "Given its likely engagement with PD-1 in tumor immunotherapy, PCSK9 might provide useful insight into tumor development and immune treatment response." (PMID 37860186, 2023). "However, we cannot exclude the possibility that increases in cholesterol accumulation were a result of the elevations in tumor growth stimulated by PCSK9." (PMID 36588164, 2023). "However, tumor grades 1–2 showed an increase in PCSK9 signal (p = 0.0003) compared to tumor grade 3." (PMID 37103355, 2023). "PCSK9 inhibition could induce the cell apoptosis of many malignant tumor cells and suppress the progression of lung LUAD." (PMID 37189138, 2023). "Moreover, tumor growth was further delayed by the PCSK9 inhibitor in combination with the CD137 agonist with long-term survival of the host mice in the doublet group." (PMID 37025995, 2023). "Hence, about the relationship between sex-related PCSK9 and tumor, it needs to be further explained." (PMID 37860186, 2023). "The use of PCSK9 siRNA resulted in an anti-tumor activity by the induction of apoptosis." (PMID 36552895, 2022). "In grade I/II, there are more colon caner patients with low expression of PCSK9 in tumor cells." (PMID 36242053, 2022). "On the other hand, PCSK9 protein levels in the tumors were not linked to tumor grade and in another case report, PCSK9 mRNA levels were even 4-fold higher in the tumor than in the adjacent tissues." (PMID 35162992, 2022). "Recent researched have confirmed the anti-tumor effects of PCSK9 inhibition." (PMID 36242053, 2022). "In our research, we found that PCSK9 blockade could eliminate increased tumor-infiltrating Tregs induced by PD-1 inhibitor." (PMID 36003387, 2022). "After observing the tumor size, weight, and survival for 60 days, they found that the nanoliposomal anti‐PCSK9 vaccine could alleviate tumor growth by 21.2%, and prolong survival by 4.2%, even though the difference was not significant." (PMID 34962050, 2022). "The up-regulation of PCSK9 mRNA in CRC was independently demonstrated in paired tumor and adjacent normal tissues in Hong Kong (N = 150; P < 0.0001) and TCGA COADREAD cohorts (N = 50; P < 0.0001), and in unpaired CRC (N = 624) and adjacent normal tissues (N = 51) from TCGA (P < 0.0001)." (PMID 35803966, 2022). "The anti-tumor effects of PCSK9 inhibitors need to be further explored." (PMID 35918332, 2022). "Interestingly, HCC tumor tissues presented high expression of PCSK9, which is correlated with poor prognosis after curative resection." (PMID 36612001, 2022). "Many studies have focused on the function of PCSK9 in tumor." (PMID 34962050, 2022). "Very recently, a well-conducted study reported inhibition of PCSK9, a key enzyme upregulates the cholesterol synthesis, that could enhance the antitumor immunity in the tumor microenvironment, which partially confirmed our results." (PMID 33628817, 2021).
tumor (continued). "More recently, it was revealed that PCSK9 also traffics major histocompatibility protein class I (MHC I) from the tumor cell surface to the lysosome for degradation, and that inhibition of PCSK9 can induce intratumoral infiltration by T cells and improve the response to immune check point therapy." (PMID 33770486, 2021). "Our results show for the first time that PCSK9 expression is detected in tumor-derived PDCs, indicating that modulation of cholesterol pathway could play a role in OC tumorigenesis." (PMID 34359627, 2021). "Together, these results suggested that PCSK9 acted as a tumor suppressor in HCC." (PMID 33893729, 2021). "Furthermore, we wanted to evaluate PCSK9 expression in OC tumor samples and for this, we used PDCs derived from HGSOC and LGSOC patient tumors." (PMID 34359627, 2021). "Besides limiting tumor growth when administered alone, anti-PCSK9 antibodies significantly enhanced anti-tumor efficacy of ICI therapy (anti-PD-1)." (PMID 35097027, 2021). "PCSK9 expression levels were significantly lower in HCC tissues than in adjacent non-tumor samples." (PMID 33893729, 2021). "Moreover, genetic deletion or pharmacological inhibition of PCSK9 in tumor cells can enhance the antitumor activity of CD8+ T cells by alleviating the suppressive effect on CD8+ T cells and consequently inhibit tumor progression." (PMID 33606190, 2021). "In our study, we showed that PCSK9 could promote tumor metastasis in GC partly through HSP70 up-regulation by modulating MAPK pathway." (PMID 33489919, 2020). "The silencing of PCSK9 reversed these effects, suppressing tumor metastasis in vitro and in vivo." (PMID 33489919, 2020). "In view of the finding that PCSK9 facilitates the migration and invasion of GC cells in vitro, we further tested whether PCSK9 could affect tumor progression in vivo." (PMID 33489919, 2020). "Notably, the up-regulation of PCSK9 expression in GC tissues was related to tumor progression and poor survival." (PMID 33489919, 2020). "Given that MAPK pathway is implicated in tumor cell proliferation, differentiation, and apoptosis, we hypothesized that it could be involved in PCSK9-induced tumor progression as well." (PMID 33489919, 2020). "Additionally, we identified PCSK9 as a harmful molecule in tumor progression, which indicates that the inhibition of PCSK9 can be a novel and promising therapeutic approach to GC." (PMID 33489919, 2020). "Interestingly, serum and tumor PCSK9 level was upregulated in HepG2-tumor-bearing mice having access to water containing glucose." (PMID 30386595, 2018). "Interestingly, murine PCSK9 level was reduced in serum of non-tumor-bearing mice from group II as compared to group I." (PMID 30386595, 2018). "On these lines, we hypothesized that glucose could have effect on PCSK9 expression in HCC tumor which may have implications in altering LDLc level in the host." (PMID 30386595, 2018). "By contrast, the reduction of LDL-R by PCSK9 inhibitors may result in an increased intracellular content of cholesterol within tumor cells that could sustain ERRα activation." (PMID 30254608, 2018). "To finally confirm the function of miR-224 and PCSK9, we performed tumor formation assay in vivo." (PMID 28036293, 2017). "Recent findings from our laboratory also suggest a role for PCSK9 in enhancing tumor metastasis." (PMID 23675525, 2013). "The findings establish a mechanistic link between amino acid metabolism and cholesterol metabolism within the tumor microenvironment where tumor cells sense methionine to regulate PCSK9 expression, highlighting promising combination therapeutic strategies that may greatly benefit MSS CRC patients." (PMID 40125618, 2025).
tumor (continued). "Thus, targeting PCSK9 presents substantial therapeutic potential; it may curtail metastasis, delay disease progression, and modulate immune responses within the tumor microenvironment." (PMID 41458606, 2025). "Mechanistically, PCSK9 overexpression has been associated with enhanced phosphorylation of mitogen-activated protein kinases (MAPKs), including p38MAPK, ERK1/2, and JNK, which may facilitate tumour cell migration and invasion." (PMID 41008547, 2025). "Moreover, PCSK9 was found to have regulatory effects on DCs in non-tumor diseases." (PMID 38600469, 2024). "Combining PCSK9 inhibitors could enhance the efficacies of OVA-II tumor vaccine monotherapy." (PMID 38600469, 2024). "Therefore, we hypothesize that PCSK9 inhibits the expression level of MHC-II on the surface of tumor cells by activating the MAPK signaling pathway." (PMID 38600469, 2024). "By establishing a tumor-bearing mouse model of CRC with Fh1 expression deficiency, we confirmed that the therapeutic effect of PD-1 antibodies alone was suboptimal in mice with low Fh1 expression, which was improved by combination with a protein invertase subtilisin/kexin 9 (PCSK9) inhibitor." (PMID 38398104, 2024). "Moreover, research focusing on patient-derived xenografts (PDX) and/or tumor organoids in humanized mice and/or transgenic mice could greatly contribute to expanding our knowledge of the intricate roles PCSK9 plays within the TIME of human malignancies." (PMID 38185721, 2024). "Additionally, PCSK9 may regulate the tumor immune matrix score, immune cell infiltration, immune checkpoint expression, and major histocompatibility complex expression." (PMID 38600469, 2024). "Indeed, as reviewed elsewhere, several preclinical studies have hypothesized that inhibition of PCSK9 through genetic depletion, monoclonal antibodies, nano-liposomal vaccination, or siRNA might effectively suppress tumor growth." (PMID 38611089, 2024). "Hence, PCSK9 inhibitors may develop peripheral immunological tolerance against tumor cells improving T-lymphocyte identification." (PMID 38509261, 2024). "Interestingly, it was reported that PCSK9 inhibitors could decrease tumor metastasis in tumors by inhibiting the MAPK pathway through HSP70 up-regulation." (PMID 37896137, 2023). "However, the relationship between PCSK9 and tumor needs further proof." (PMID 37305043, 2023). "Notably, Pcsk9-KO CAFs cannot rescue tumor growth in glucose-limited medium." (PMID 37898598, 2023). "Therefore, we postulate that metformin may also affect the generation of vessel co-option tumours in CRCLM via regulation of PCSK9 and LDL-C levels." (PMID 36979711, 2023). "As expected, the results revealed higher glucose (to lesser extent glutamine) consumption as well as lactate and glutamate production in the absence of PCSK9, suggesting that PCSK9 deficiency strengthens the glycolytic phenotype and consumption of glutamine of tumor cells." (PMID 36612001, 2022). "Finally, PS inhibited the locoregional tumor recurrence by decreasing PCSK9 levels." (PMID 36552895, 2022). "In addition to these experimental data, PCSK9 targeting in vivo revealed a previously unknown function of PCSK9 in promoting tumor vascularization." (PMID 36612001, 2022). "Therefore, the impact of PCSK9 deficiency on tumor growth was independent of cholesterol metabolism." (PMID 33677469, 2021). "Therefore, PCSK9 decreases the cytotoxic T lymphocyte response against the tumor." (PMID 33834043, 2021). "Also, tumor tissue from group IV had an increase in PCSK9 protein level as compared to group III." (PMID 30386595, 2018).
tumor (continued). "Studies have shown that PCSK9 regulates signaling pathways such as PI3K/Akt, MAPK, and Wnt/β‐catenin, thus influencing tumor cell proliferation, survival, and angiogenesis." (PMID 40145543, 2025). "PCSK9 inhibitors improve ICI efficacy by promoting immune cell activation and reducing tumor‐induced immune suppression." (PMID 41085102, 2025). "In anaplastic thyroid carcinoma, PCSK9 drives the lysosome-dependent degradation of E-cadherin, thereby facilitating EMT and tumour spread." (PMID 41008547, 2025). "Lowering cholesterol levels through genetic or pharmacological inhibition of PCSK9 suppresses MDSC expansion, pro-tumoral TAM accumulation, and tumor progression in a RORγ-dependent manner, thereby unleashing specific anti-tumor immunity." (PMID 41417432, 2025). "Taken together, these results demonstrated that tumor PCSK9 expression is modulated by methionine alterations both in vitro and in vivo, and participates in DMR‐regulated CRC tumor progression." (PMID 40125618, 2025). "PCSK9 reduces E-cadherin expression, increases N-cadherin levels, and enhances matrix metalloproteinase-9 (MMP9) activity, thereby promoting tumor cell migration and invasion." (PMID 40563628, 2025). "Disrupting these lipid raft structures-via statins or anti-PCSK9 antibodies-impairs budding, suppresses PGCC-derived tumor repopulation, and enhances radiosensitivity in vitro and in vivo." (PMID 41330885, 2025). "The researchers created a bioactive peptide derived from PCSK9 that acts as a competitive inhibitor of PCSK9 palmitoylation, thereby reducing AKT phosphorylation and boosting the anti‐tumor efficacy of sorafenib in HCC." (PMID 40145543, 2025). "Emerging research suggests PCSK9 also degrades MHC-I, reducing tumor immunogenicity and restricting lymphocyte activity." (PMID 40563628, 2025). "In our study, injection of TNBC cells with either knockdown or overexpression of PCSK9 into NOD/SCID mice resulted in significant decreases and increases in orthotopic and metastatic tumor sizes compared to those in the control group." (PMID 40192514, 2025). "In this study, a combined therapy involving DMR with PD‐1 blockade was conducted in MSS CRC tumor model, and it was found that DMR promotes the infiltration and function of CD8+ T cells and potentiates PD‐1 blockade therapy by decreasing PCSK9 expression." (PMID 40125618, 2025). "We selected 4 candidate genes (PCSK9, SGPP1, PGK1 and FOXM1) reported to be closely involved in tumour progression and radioresistance for further analysis." (PMID 39548064, 2024). "Our findings reveal that combining a PCSK9 inhibitor with PD-1 antibodies promotes CD8+ T cell clonal expansion and significantly enhances tumor immunotherapy in an FH-low expression mouse model of CRC." (PMID 38398104, 2024). "Next, we explored the relationship between PCSK9 expression and TNM stage in 33 tumor types in the TCGA cohort." (PMID 38600469, 2024). "Treatment with the PCSK9 inhibitor PF-06446846 can effectively potentiate the antitumor immunity of CD8+ T cells and suppress tumor growth." (PMID 39402302, 2024). "To further explore the role of PCSK9 in the TME, we established the MFC-bearing 615 mouse model and illustrated the effective tumor suppression of PCSK9i." (PMID 38600469, 2024). "In this study, in tumor tissue a statistically significant reduction of PCSK9 mRNA levels (PCSK2, PCSK5, PCSK7, PCSK9) and an increase in PCSK1 mRNA expression was demonstrated." (PMID 38509261, 2024). "Finally, even though we were able to show that PCSK9 expression was associated with tumor immune cell infiltration and patient survival, we were not certain that PCSK9 affected clinical survival through the immunological system; this requires further clinical trial verification." (PMID 37860186, 2023).